ROR1 (ROR family WNT receptor 1)
Diseases named in the same sentence as ROR1 in open-access papers (continued):
Sharing a sentence is not in itself a finding about the gene and the disease.
tumor (continued). "While ongoing research has begun to reveal the pro-tumorigenic functions of ROR1 and ROR2 in cancer, the mechanisms underlying their regulation and their context-dependent functionality in the distinct tumor entities, which has caused conflicting observations, are still largely unknown." (PMID 33445713, 2021). "As a result of these mechanisms, the Wnt5A/ROR1 signaling axis plays a negative role associated with enhanced tumor cell migration or induces a transcriptional response leading to the expression of genes that contribute to cell proliferation, survival, EMT, or therapy resistance." (PMID 34376211, 2021). "Also, endogenous T cells have to be activated by BiTEs to act on ROR1+ tumor cells." (PMID 29850623, 2018). "Thus, our results implied that the ROR1-cFab could effectively inhibit tumor cell migration in a time-dependent manner." (PMID 29212222, 2017). "However, the molecular mechanism of the tumor-specific ROR1 expression remains unclear and investigations are still ongoing." (PMID 28427197, 2017). "Furthermore, high ROR1 levels on tumor cells correlate with metastases and poor outcomes." (PMID 28811962, 2017). "Interestingly, a relatively low concentration of ROR1 BiTE was required (nanogram quantities) when compared with doses (microgram quantities) of conventional antibodies used in clinic, to mediate killing of tumor targets." (PMID 28811962, 2017). "Hence, ROR1 is a suitable marker for distinguishing tumor B cells from healthy cells." (PMID 28117741, 2017). "Similarly, ROR1RCD28+ and ROR1RCD137+ T cells generated from PBMC of a patient with CLL were able to lyse EL4-ROR1 and autologous tumor cells (ROR1+; isolated with CD19-specific magnetic beads), while autologous T cells and parental EL4 (both ROR1neg) cells were spared." (PMID 26030772, 2015). "Moreover, such cells could eliminate ROR1+ tumor xenografts, especially T cells expressing ROR1RCD137." (PMID 26030772, 2015). "A ROR1 protein with a molecular size of ≈120 kD could be detected in tumor-tissue lysates." (PMID 22403610, 2012). "We found that ROR1 could interact with casein kinase 1 epsilon (CK1ε) to activate phosphoinositide 3-kinase-mediated AKT phosphorylation and cAMP-response-element-binding protein (CREB), which was associated with enhanced tumor-cell growth." (PMID 22403610, 2012). "This approach preserved the antitumor function of ROR1-CAR-T cells in vitro and within 3D tumor models." (PMID 40281554, 2025). "ROR1-CAR-T cell application has proven the release of cytokines and cytolytic activities that aid in tumor destruction." (PMID 39755633, 2025). "To further assess potential on-target, off-tumor effects, we analyzed CD155 expression patterns alongside reference genes (EGFR, ERBB2, and ROR1), which are currently being investigated in clinical trials for CAR-T therapies." (PMID 40478751, 2025). "ROR1 CAR-T cells exhibited significantly higher cytotoxicity against the NCI-H1299 cell line, while demonstrating limited activity against primary tumor cells from patients who had undergone multiple rounds of treatment." (PMID 39849645, 2025). "We employed ROR1 knockdown in a TNBC cell line and screened the differentially methylated regions to identify functionally silenced tumor suppressor genes." (PMID 40427627, 2025). "The findings demonstrate that propionate and butyrate inhibit anti‐ROR1 CAR T‐cell function by reducing infiltration, cytotoxicity, and cytokine release while preserving junctional integrity within the tumor model." (PMID 40249196, 2025). "As anticipated, PC-PUFA2 synergized with ROR1 CAR-T cells to induce significant cell death of both NCI-H1299 cells and primary tumor cells." (PMID 39849645, 2025). "The anticancer activity of zilovertamab vedotin is primarily due to binding of the ADC to ROR1-expressing tumor cells, internalization of the ADC–ROR1 complex with trafficking to tumor cell lysosomes, and release of MMAE via lysosomal proteolytic cleavage." (PMID 40762544, 2025).
tumor (continued). "For instance, NVG-111 (NCT04763083) is a novel bispecific that targets ROR1 and CD3, harnessing T cells against a more selective target to reduce off-tumor toxicity." (PMID 40723181, 2025). "The ROR1-reactive HTLs selectively recognized ROR1+ HNSCC cell lines in an HLA-DR-restricted manner, indicating that the ROR1403–417 epitope is naturally processed and presented by tumor cells." (PMID 40723210, 2025). "Through RRBS we observed that CREB3L1, a known tumor suppressor in TNBC, was one of the genes that had significant differential methylation patterns when ROR1 was knocked down in MDA-MB-231 cells." (PMID 40427627, 2025). "This study investigated the potential of combining receptor tyrosine kinase-like orphan receptor 1 (ROR1)-targeting CAR-T cells with ferroptosis inducers to promote ferroptosis of tumor cells and enhance anti-tumor efficacy." (PMID 39849645, 2025). "In a parallel study, we demonstrated that ROR1 is highly expressed on NB and developed anti-ROR1-CAR-modified NK cells, and these anti-ROR1- CAR-NK cells showed significantly enhanced in vitro and in vivo anti-tumor effect against NB." (PMID 39895691, 2025). "By treating NCI-H1299 cell line and primary tumor cells (obtained from patients) with the ferroptosis inducer RSL3, the authors observed increased sensitivity to IFNγ secreted by ROR1 CAR T-cells." (PMID 41339932, 2025). "Both dosages of ROR1 DAC significantly inhibited tumor growth compared to PBS, ROR1 mAb control, MZ1, and isotype DAC control." (PMID 39816690, 2025). "Based on the percentage expression of cells in a given cluster, the log FC value, and the corresponding biological function, we ultimately identified ROR1 as a marker for tumor cells in TGCT and PRKD1 as a marker for MP3 tumor cells in D‐TGCT." (PMID 40126353, 2025). "Inhibiting ROR1 activation by treatment with strictinin, a small molecule inhibitor, resulted in the downregulation of the PI3K/AKT pathway, thus decreasing tumor cell migration and survival and increasing apoptosis." (PMID 40427627, 2025). "ROR1 inhibition via an anti-ROR1 monoclonal antibody or knockdown via shRNA in ovarian PDX decreased sphere formation efficiency and reduced tumor formation in xenografts of virgin mice." (PMID 40869147, 2025). "These PDX models were evaluated in flow cytometry for the expression of the Receptor tyrosine kinase-like orphan receptor 1 (ROR1), a known tumor-specific target." (PMID 38903501, 2024). "Many are designed to bring immune cells in proximity with tumor cells by targeting both immune markers (CD137/4-1BB, CD27, PD-1, OX-40) and tumor markers (B7-H3, CD47, PD-L1, 5T4, ROR1, claudin, GPC3, HLA-G, PSCA)." (PMID 38254823, 2024). "Similar results were obtained in DLBCL ROR1 positive cells, where KAN0441571C induced apoptosis in tumor cells and in zebra fish models." (PMID 39551787, 2024). "Mechanistically, ROR1 and lncRNA DLEU2 overexpression led to enhanced tumor cell proliferation, inhibition of apoptosis, cell-cycle dysregulation, chemoresistance, as well as BC cell’s abilities to invade, migrate, develop spheroids." (PMID 38296962, 2024). "The average weight of tumors developed from either Ror1- or Rif-KO PC9 cells was significantly lower than that developed from control PC9 cells, indicating that Ror1and Rif play crucial roles in tumor development of PC9 cells in vivo." (PMID 37703992, 2023). "The oncogenic Wnt receptors ROR1/2 are transferred via EVs to the surface of ROR-negative cancer cells, in which they induce an aggressive phenotype supporting tumor progression." (PMID 37430307, 2023). "The first-in-class ROR1 inhibitor (KAN0439834), which binds to the intracellular tyrosine kinase (TK) domain of ROR1, induced apoptosis of CLL cells and inhibited tumor cell growth in NOD/SCID mice xenotransplanted with human CLL cells." (PMID 37111634, 2023). "ROR1-CAR T cells actively entered the arterial medium flow in the dynamic culture setup and adhered to and invaded the tumor mass." (PMID 38106674, 2023).
tumor (continued). "These contain known cancer-testis antigen genes (MEGA5, MEGA1, TEX15, PNMA5 and ROR1) and a number of new candidate genes (PAX2, NTN4, NTNG2 and PDE10A), these genes can be used as tumour markers or potential therapeutic targets with some clinical value." (PMID 37994961, 2023). "In cancer cells, ROR1 cooperates in pro-survival pathways such as PI3K/AKT, EGFR, and MET signaling to enhance tumor cell growth and survival, EMT (epithelial–mesenchymal transition), and metastasis." (PMID 37400436, 2023). "In previous reports, we have described the effects of two small-molecule ROR1 inhibitors (KAN0439834 and KAN0441571C) targeting the cytoplasmic tyrosine kinase domain that dephosphorylated ROR1 and induced tumor cell apoptosis." (PMID 37111634, 2023). "The presence of ROR1 and pSTAT3 in both epithelial cancer cells and stromal cells clearly indicates that ROR1/STAT3 signaling sustains the OC tumor microenvironment." (PMID 37400436, 2023). "designed a logically gated ROR1-targeted CAR-T cell that reduced off-target toxicity and selectively targeted tumor cells." (PMID 38187386, 2023). "It has been demonstrated that those ROR1 CAR-T cells are able to infiltrate the tumor tissues and eradicate several layers of tumor cells." (PMID 36831396, 2023). "ROR1 small molecule inhibitor in hematologic malignancies, including MCL, induced significant apoptosis of tumor cells in vitro as well as the inhibition of several important signaling pathways for tumor cell survival." (PMID 36297673, 2022). "The ROR1 inhibitor KAN0441571C seemed to act synergistically with these drugs, enhancing tumor cell death." (PMID 36297673, 2022). "NVG-111, a bispecific antibody targeting ROR1 and CD3, showed anti-tumor effects by T-cell mediated cytotoxicity in preclinical data." (PMID 36557069, 2022). "Recently, the application of ROR1-CAR-T cells in a 3D microphysiologic tumor models of TNBC presented cytolytic activity and cytokine secretion that favor tumor killing." (PMID 35414783, 2022). "Knockdown of DKK1 enhanced CS-stimulated tumor invasion activity of MDA-MB-231 cells, suggesting that DKK1 sequesters CS to block ROR1/JNK signaling." (PMID 35712490, 2022). "summarized that ROR1 was involved in inhibiting cell apoptosis, enhancing the EGFR signaling pathway, and inducing tumor epithelial-mesenchymal transformation (EMT)." (PMID 35935930, 2022). "Our study shows that ROR1 is commonly expressed in SCLC, and that it is a potential therapeutic target that would have broad therapeutic value to SCLC patients in a targeted, tumor-specific manner." (PMID 34088900, 2021). "ROR1 expression was identified in 93% (52/56) of SCLC tumors, while BCL2 expression was identified in 86% (48/56) of SCLC tumors, and 83% (45/56) of SCLC tumors showed expression of both ROR1 and BCL2 in the same tumor cells." (PMID 34088900, 2021). "Although the majority of CLL patients harbor high levels of ROR1-positive tumor cells in blood, ~5% of CLL cases exhibited negligible ROR1 expression." (PMID 33445713, 2021). "Although tumor-specific antigens are expressed by CLL cells (e.g., the ROR1 antigen) and are further effectively presented by MHC class I and class II molecules, cognate T cells fail to mount strong anti-tumor immune responses." (PMID 34209724, 2021). "designed a Logic-Gated ROR1 CAR that can save healthy tissues and target tumor cells, addressing the issue of off-target toxicity." (PMID 34566963, 2021). "We have previously shown in preclinical models that small molecules inhibiting ROR1, KAN0439834 and KAN0441571C, induced tumor cell death in CLL and DLBCL cells which express activated ROR1." (PMID 35844694, 2021). "Receptor tyrosine kinase-like orphan receptor 1 (ROR1) is an oncofetal protein that is emerging as a therapeutic target and is co-expressed with BCL2 in multiple tumor types due to microRNA coregulation." (PMID 34088900, 2021).
tumor (continued). "Based on cirmtuzumab’s high binding specificity towards ROR1-positive cells and its rapid internalization into target cells, this approach promises to safely deliver and release MMAE into the tumor cell." (PMID 33445713, 2021). "In particular, silencing of ROR1 in NSCLC cells disrupts their ability to escape anoikis and anchorage-dependent programmed cell death, and shows decreased primary tumor growth when the cells are transplanted into nude mice." (PMID 33172431, 2020). "In this context, the receptor tyrosine kinase-like orphan receptor 1 (ROR1) can be considered a putative TAA for CLL, being a cancer stem cell antigen almost exclusively expressed on tumor cells and involved in the biology and aggressiveness of the disease." (PMID 33312177, 2020). "Expression of anti-ROR1 CAR was induced only upon engagement of EpCAM or B7-H3 to the syNotch receptor, thus only dual positive tumour cells were eliminated, and on-target off-tumour toxicities were prevented." (PMID 32824734, 2020). "We recently described a first-in-class ROR1 small molecule inhibitor (SMI) (KAN0493834) inducing specific apoptosis of CLL cells and tumor cell reduction in immunodeficient mice xenotransplanted with human CLL cells." (PMID 32586008, 2020). "Indeed, it has been demonstrated that ROR1 has an important therapeutic role in such a neoplastic disease because glucocorticoids anti-inflammatory agents (generally administred as adjuvant to chemotherapy) may induce chemoresistance by promoting ROR1-mediated stemness." (PMID 33172431, 2020). "In zebra fishes transplanted with a ROR1+ DLBCL cell line, KAN0441571C induced a significant tumor reduction." (PMID 32586008, 2020). "Conclusively, our results show that DEX treatment elevated ROR1 expression, which in turn enhanced RhoA, YAP/TAZ, and BMI-1 levels in OC tumor cells and is indicative of a DEX-mediated stemness phenotype via ROR1 signaling." (PMID 32989221, 2020). "It was identified that the inhibition of ROR1 via small interfering RNA treatment significantly improved the anti-proliferation and apoptosis-inducing roles of erlotinib in TKI-resistant tumor cells." (PMID 31452776, 2019). "Taken together, these studies demonstrate the existence of a Wnt5a/ROR1–YAP/TAZ feedback loop that modulates the CSC phenotype, tumor progression, metastasis and, ultimately, drug resistance." (PMID 31382410, 2019). "ROR1 is involved in proliferation, survival, EMT and metastasis of tumor cells in various malignancies." (PMID 29856777, 2018). "By ROR1 fluorescence labeling, tumor B cells were recognized and then the AFM tip carrying rituximab (a monoclonal anti-CD20 antibody) was moved to tumor B cells to probe the CD20s on cell surface." (PMID 28117741, 2017). "This notion is supported by the example of ROR1 CARs, where the length of extracellular spacer was decisive in determining the CAR tumor recognition." (PMID 28515942, 2017). "The expression of ROR1 protein was evaluated by Western blot analysis of lysates from lung ADC and their matched non-tumor tissue samples." (PMID 27830754, 2016). "In summary, effector function of CAR+ T cells, as manifested by IFNγ expression, was restricted to ROR1+ tumor cells and ROR1RCD28+ T cells produced more IFNγ than did ROR1RCD137+ T cells in response to ROR1." (PMID 26030772, 2015). "Based upon these collective results we propose that ROR1 interacts with CK1ε to activate PI3K/AKT/CREB, which in turn induces expression of genes that can enhance resistance to apoptosis and/or promote tumor cell growth." (PMID 22403610, 2012). "However, aberrant re‐expression of ROR1 has been observed in several epithelial cancers, including colorectal cancer (CRC), where it contributes to tumor progression, epithelial–mesenchymal transition, and metastasis." (PMID 40249196, 2025). "Although these patients showed a slightly higher proportion of ROR1‐high tumours, the difference was not statistically significant." (PMID 41355329, 2025).
tumor (continued). "This suggests that Q2/3W dosing has the potential to maximize target engagement via ADC binding to ROR1-expressing tumor cells without increasing MMAE-related toxicities." (PMID 40762544, 2025). "Of the 10 tumor samples obtained from ICB-resistant patients, eight (80%) were positive for ROR1, with five samples showing strong positivity and three showing weak positivity, while nonmalignant cells in adjacent normal tissues exhibited minimal ROR1 expression." (PMID 39849645, 2025). "Additional limitations included lack of correlation of response with baseline ROR1 level, lack of ROR1 gene expression assayed in tumor specimens, and lack of consensus of which antibodies are best suited for detection of ROR1 on formalin-fixed cancer tissue." (PMID 38408999, 2024). "The ROR1 FC data generated from CLL and HCL samples was based only on a membrane signature considering that membrane distribution is required to assess ROR1 as a tumour target for new therapeutic modalities such as ADC, TCE, or CAR-T." (PMID 39495778, 2024). "Second, we tested over 1000 samples but did not test all tumor types reported to be positive for ROR1." (PMID 38791952, 2024). "Analysis of ROR1 mRNA expression in tumor tissue of PDAC patients did not reveal differences in overall survival." (PMID 38846943, 2024). "ROR1 positive/negative tumour cell status was the common parameter available from both FC and IHC analyses to compare all investigated haematological cancer types, including our reference solid tumour indication TNBC." (PMID 39495778, 2024). "Unfortunately, the patient had no baseline or on-study tumor biopsy for ROR1 immunohistochemical assay." (PMID 38408999, 2024). "In mouse KP1233 (KP) tumor cells, CAR-T cells targeting receptor tyrosine kinase-like orphan receptor 1 (ROR1) cannot effectively invade tumors and are dysfunctional, while anti-PD-1 / PD-L1 can enhance CAR-T cell efficacy in cyclophosphamide (Ox) / oxaliplatin (Cy)-treated cancers." (PMID 38664743, 2024). "For instance, receptor tyrosine kinase-like orphan receptor 1 (ROR1)-CAR-T cells were modified to incorporate synNotch receptors with specificity for EpCAM or B7-H3, both present on ROR1 + tumor cells but not on ROR1 + stromal cells." (PMID 38622705, 2024). "No ROR1 positive tumour cells were detected in either bone marrow core biopsies or aspirate clot tissue." (PMID 39495778, 2024). "Moreover, in the case of CLL ROR1 positive cells that are resistant to ibrutinib, KAN0441571C and venetoclax increased the rate of apoptosis in tumor cells." (PMID 39551787, 2024). "In addition, ROR1 values from frozen and fresh CLL samples were similar with 77.0 and 77.3% of positive tumour cells, respectively." (PMID 39495778, 2024). "As such, we examined the kinetics by which hum-VHH-2-LC and the benchmark R11-scFv-1 induced expanded T cell mediated killing of ROR1-positive MDA-MB-231, ROR1-negative T-47D tumor cells or a 1:1 mixture of both cells." (PMID 38455046, 2024). "On the other hand, the interaction between Wnt5a/ROR1 signaling and YAP/TAZ pathway may enhance cell proliferation and tumor development." (PMID 39551787, 2024). "Our studies show that the non-canonical Wnt signaling via ROR1/2 receptors can regulate phenotypic outputs in OC, contributing to tumor heterogeneity and disease progression." (PMID 37400436, 2023). "KAN0441571C is the second generation of a ROR1 tyrosine kinase inhibitor (TKI) that induced apoptosis and death of DLBCL cells and small cell carcinoma of the lung, and that acted synergistically with venetoclax on tumor cell apoptosis." (PMID 37111634, 2023). "At all cell ratios tested, ROR1 CAR-T cells destroyed ROR1+ tumor cells but not normal cells, showing the specificity of this type of therapy." (PMID 36873868, 2023).